METRNL (meteorin like, glial cell differentiation regulator)
Description:
Hormone induced following exercise or cold exposure that promotes energy expenditure. Induced either in the skeletal muscle after exercise or in adipose tissue following cold exposure and is present in the circulation. Able to stimulate energy expenditure associated with the browning of the white fat depots and improves glucose tolerance. Does not promote an increase in a thermogenic gene program via direct action on adipocytes, but acts by stimulating several immune cell subtypes to enter the adipose tissue and activate their prothermogenic actions. Stimulates an eosinophil-dependent increase in IL4 expression and promotes alternative activation of adipose tissue macrophages, which are required for the increased expression of the thermogenic and anti-inflammatory gene programs in fat. Required for some cold-induced thermogenic responses, suggesting a role in metabolic adaptations to cold temperatures (By similarity).
Tractability: Antibody: UniProt places it where antibodies can reach, with medium confidence; UniProt predicts a signal peptide or a membrane-spanning region; its Gene Ontology location is reachable by antibodies, with medium confidence.
Gene: Protein-coding gene on chromosome 17 (83,079,609 to 83,095,122, forward strand). Ensembl gene ENSG00000176845.
Subcellular location: Secreted
Gene Ontology:
Molecular function: hormone activity
Biological process: brown fat cell differentiation; energy homeostasis; fat cell differentiation; negative regulation of inflammatory response; positive regulation of brown fat cell differentiation; response to cold; response to muscle activity; signal transduction
Cellular component: extracellular exosome; extracellular region
Genetic constraint (gnomAD): Loss-of-function variants: 8 observed, 16.99 expected, observed/expected ratio (o/e) 0.47, 90% interval 0.28 to 0.85. The upper end of that interval is the gene's LOEUF score, 0.85, which puts it in group 3 of 6, group 1 being the genes least tolerant of losing a copy. Missense variants: 361 observed, 371.24 expected, observed/expected ratio (o/e) 0.97, 90% interval 0.89 to 1.06. Synonymous variants: 193 observed, 170.98 expected, observed/expected ratio (o/e) 1.13, 90% interval 1 to 1.27.
Homologues: Orthologues: macaque METRNL (96% identical), dog METRNL (83% identical), chimpanzee METRNL (81% identical), pig METRNL (81% identical), rat Metrnl (78% identical), mouse Metrnl (77% identical), rabbit METRNL (77% identical), guinea pig METRNL (75% identical), tropical clawed frog metrnl (57% identical), zebrafish metrnla (51% identical), zebrafish metrnlb (45% identical). Paralogues in human: METRN (41% identical).
Diseases named in the same sentence as METRNL in open-access papers:
METRNL is named in the same sentence as 54 diseases in open-access papers, as found by Europe PMC text mining. Sharing a sentence is not in itself a finding about the gene and the disease. The quoted sentences say what the papers report.
Obesity (12 papers, 2012 to 2025). Accumulation of substantial excess body fat. "Previous studies have demonstrated that irisin and METRNL levels are positively associated with higher BMI and various obesity- and T2D-related parameters." (PMID 31635130, 2019). "Additionally, METRNL and irisin showed significant correlation with various metabolic biomarkers associated with T2D and Obesity." (PMID 31635130, 2019). "Our group previously reported an increase in the levels of two adipomyokines, irisin and Meteorin-like (METRNL) in T2D, which was further exacerbated with obesity." (PMID 34777249, 2021). "In this study plasma levels of osteoactivin and OPG were shown to be increased with obesity and T2D concomitant with increased levels of irisin and METRNL." (PMID 34777249, 2021). "Circulating levels of irisin and METRNL were significantly higher in T2D and obesity, as shown in our previous report." (PMID 34777249, 2021). "Our data shows elevated METRNL plasma levels in individuals with T2D, further exacerbated with obesity." (PMID 31635130, 2019). "In conclusion, our study confirms an increased expression level of both irisin and METRNL proteins in obesity and T2D." (PMID 31635130, 2019). "These regions were found near genes associated with obesity (MCR4), imprinting (GNAS), and glial cell formation (METRNL)." (PMID 22761590, 2012). "In mouse models, METRNL increased in vivo in exercised mice, suggesting that METRNL is secreted during repeated muscle contraction, and injected METRNL improved glucose tolerance in mice with high‐fat‐diet‐induced obesity or diabetes." (PMID 39415606, 2025). "METRNL is an adipokine highly expressed in white adipose tissue, with comparable expression between adipocytes and stromal cells and is regulated by adipogenesis and obesity." (PMID 38201289, 2023). "We hypothesized that an interaction exists between adipomyokines namely, irisin and METRNL, and various molecules involved in bone remodeling in individuals with obesity and T2D." (PMID 34777249, 2021). "Considering the involvement of adipomyokines in bone metabolism and the association between diabesity and bone loss, the aim of this study was to investigate the potential link between irisin, METRNL and various molecules involved in bone remodeling in people with obesity and T2D." (PMID 34777249, 2021). "METRNL also shows an anti-inflammatory role, especially in reducing adipose inflammation, increasing the expression of M2 macrophages in adipose tissue, and improving insulin resistance typical of obesity." (PMID 33807959, 2021). "Hence, METRNL an interesting target to investigate in relation to metabolic disorders such as obesity and diabetes." (PMID 31635130, 2019). "In conclusion, our findings suggest that there is a dysregulation in the expression of various markers in the musculoskeletal system mainly irisin, METRNL, osteoactivin and OPG, which may result in the development of various complications associated with obesity and T2D." (PMID 34777249, 2021).
Insulin resistance (10 papers, 2018 to 2024). Increased resistance towards insulin, that is, diminished effectiveness of insulin in reducing blood glucose levels. "METRNL acts as an insulin sensitizer and holds promising potential as a therapeutic target for addressing insulin resistance." (PMID 38681576, 2024). "METRNL also attenuates inflammation and insulin resistance in skeletal muscle via AMP-activated protein kinase and PPARδ-dependent pathways." (PMID 36936161, 2023). "Further research showed that peroxisome proliferator–activated receptor-γ (PPARγ) enhances the capacity of METRNL to antagonize insulin resistance in adipose tissue." (PMID 36936161, 2023). "siRNA targeting PPARδ markedly blocked the effects of METRNL on palmitate-induced inflammation and insulin resistance, demonstrating that METRNL ameliorates palmitate-induced inflammation and insulin resistance through PPARδ-dependent signaling." (PMID 30213948, 2018). "In conclusion, the current study is the first to show that METRNL ameliorates lipid-induced inflammation and insulin resistance via AMPK- or PPARδ-dependent signaling in skeletal muscle of mice." (PMID 30213948, 2018). "Treatment of C2C12 cells with METRNL markedly suppressed palmitate-induced insulin resistance, as detected by an impairment of insulin-stimulated IRS-1 and Akt phosphorylation." (PMID 30213948, 2018). "To establish the possible links between METRNL, inflammation and insulin resistance more clearly, we performed preliminary animal experiments." (PMID 30213948, 2018). "In the current study, we report for the first time that METRNL alleviates inflammation and insulin resistance and induces fatty acid oxidation through AMPK or PPARδ-dependent signaling in skeletal muscle." (PMID 30213948, 2018). "In the present study, we investigated the effects of the novel myokine, METRNL, on lipid-induced inflammation and insulin resistance." (PMID 30213948, 2018). "In addition, METRNL has been reported to attenuate lipid-induced inflammation and insulin resistance via AMPK- or PPARδ-dependent pathways in skeletal muscle of mice." (PMID 38914997, 2024). "A previous study reported that METRNL could alleviate lipid‐induced inflammation and insulin resistance via AMPK or PPARδ‐dependent pathways." (PMID 31859449, 2020). "β-Aminoisobutyric acid (BAIBA) and Meteorin-like protein (METRNL) have been reported to ameliorate inflammation and insulin resistance in skeletal muscle of high-fat diet-fed mice." (PMID 32954935, 2020).
colorectal cancer (3 papers, 2024 to 2025). A primary or metastatic malignant neoplasm that affects the colon or rectum. "It is also thought that overproduction of METRNL may be associated with advanced colorectal cancer and poor prognosis." (PMID 39044875, 2024). "Among these, CDKN2B, BOC, and METRNL showed p-values greater than 5e-8 in the colorectal cancer GWAS data." (PMID 41144378, 2025). "Recent developments indicate that METRNL plays an oncogenic role in cellular regulation in colorectal cancer and is present in colorectal adenocarcinoma." (PMID 39044875, 2024).
metabolic syndrome (3 papers, 2021 to 2023). A cluster of metabolic risk factors for CARDIOVASCULAR DISEASES and TYPE 2 DIABETES MELLITUS. "Meteorin-like protein (METRNL), also known as Meteorin-β, interleukin-41 and subfatin, is a recently identified hormone involved in metabolic regulation and considered a candidate biomarker of metabolic syndrome." (PMID 36936161, 2023).
endothelial dysfunction (2 papers, 2020 to 2023). In vascular diseases, endothelial dysfunction is a systemic pathological state of the endothelium (the inner lining of blood vessels) and can be broadly defined as an imbalance between vasodilating and vasoconstricting substances produced by (or acting on) the endothelium. "A previous study reported that low serum METRNL levels might be associated with endothelial dysfunction." (PMID 37846349, 2023). "In addition, it has been reported that low serum METRNL levels may be associated with endothelial dysfunction (El‐Ashmawy, Selim, Hosny, & Almassry, 2019)." (PMID 31859449, 2020).
Sepsis (2 papers, 2021 to 2025). Sepsis is defined as life-threatening organ dysfunction caused by a dysregulated host response to infection. "Consistent with our findings, METRNL knockout mice reportedly displayed dysregulated cytokine production and were highly susceptible to LPS in a sepsis model." (PMID 34943988, 2021). "Inhibition of the endoplasmic reticulum-Golgi (ER-Golgi) pathway through chemical inhibitors or RNA interference significantly reduced METRNL levels in the supernatant of sepsis cell models compared to control groups." (PMID 40205457, 2025). "Clinically, sepsis patients had significantly higher serum METRNL levels." (PMID 40205457, 2025). "Similarly, in the cecal ligation and puncture mouse models, serum METRNL levels were elevated over time and correlated with sepsis severity." (PMID 40205457, 2025). "Mechanistically, it mainly originates from the endothelium during sepsis, and TLR4-ERK signaling mediates the rapid secretion of METRNL via the classical ER-Golgi pathway in response to LPS stimulation." (PMID 40205457, 2025).
actinic keratosis (1 paper, 2025). A precancerous lesion of the skin composed of atypical keratinocytes. "METRNL is produced by M2‐like macrophages and is overexpressed in skin conditions like psoriasis, prurigo nodularis, actinic keratosis, and atopic dermatitis, as well as in rheumatoid arthritis synovial membranes, suggesting its role in influencing innate and acquired immune responses." (PMID 40539722, 2025).
basal cell cancer of the skin (1 paper, 2024). "Studies investigating the relationship between METRNL and cancer show that METRNL has a protumor effect in pancreatic cancer and emphasize that it is diagnostically valuable for bladder cancer, basal cell cancer of the skin and malignant mesothelioma." (PMID 39044875, 2024).
colitis (1 paper, 2021). Inflammation of the colon. "In DSS-induced colitis, deficiency of meteorin-like protein (METRNL), secreted by IECs, deteriorated UC partially by inhibiting autophagy through the AMPK-mTOR-p70S6K pathway." (PMID 34588980, 2021).
colon carcinoma (1 paper, 2023). "The results of the study support the presence of a significant relationship between healthy colon tissue and colon carcinoma tissue in terms of METRNL and Asprosin expression." (PMID 37846349, 2023). "In the present study, the researchers tried to investigate the roles of these proteins in the pathogenesis of colon carcinoma by examining the expression of METRNL and Asprosin in healthy colon tissue and colon carcinoma tissue." (PMID 37846349, 2023). "In the present study, the researchers observed that METRNL was lower in colon carcinoma tissue than in healthy colon tissue." (PMID 37846349, 2023). "METRNL immunoreactivity was found to be significantly lower in colon carcinoma tissues than in healthy colon tissues (0.2 ± 0.06, 0.08 ± 0.03, respectively) (p < 0.001)." (PMID 37846349, 2023). "In the present study, the researchers found a significant difference in terms of METRNL and Asprosin expression between healthy colon tissue and colon carcinoma tissue and thought that these proteins might have diagnostic and treatment potential." (PMID 37846349, 2023).
dementia (1 paper, 2024). Loss of intellectual abilities interfering with an individual's social and occupational functions.
endometrial adenocarcinoma (1 paper, 2024). "In another study, it was found that METRNL expression increased as atypia increased in tissue with endometrial hyperplasia, and the highest level was in endometrial adenocarcinoma (EAC)." (PMID 39044875, 2024). "In patients with endometrial adenocarcinoma, METRNL expression was observed to be increased in carcinoma tissue compared to healthy tissue." (PMID 39044875, 2024).
exfoliation syndrome (1 paper, 2021). An autosomal dominant disorder caused by mutations in the LOXL1 gene, encoding lysyl oxidase homolog 1. "Linkage disequilibrium and epistasis analysis for this variant identified the genes LHFPL3, GALNT6, PIH1D1, ANKS1B, and METRNL as potentially involved in the etiopathogenesis of exfoliation syndrome and glaucoma, which were not previously associated with the disease." (PMID 34440405, 2021).
glaucoma (1 paper, 2021). Increased pressure in the eyeball due to obstruction of the outflow of aqueous humor. "In our study, the newly identified linked genes LHFPL3, GALNT6, PIH1D1, ANKS1B, and METRNL may be involved in the etiopathogenesis of XFS and glaucoma." (PMID 34440405, 2021).
Hypertension (1 paper, 2021). The presence of chronic increased pressure in the systemic arterial system. "Patients with hypertension had significantly higher METRNL concentrations in CSF (1117.5 pg/mL ± 673.1 pg/mL) than normotensive subjects (929.6 pg/mL ± 575.2 pg/mL) (p = 0.023)." (PMID 34362056, 2021).
osteosarcoma (1 paper, 2016). A usually aggressive malignant bone-forming mesenchymal neoplasm, predominantly affecting adolescents and young adults. "Overexpression of METRNL inhibited mineralized nodule formation by the MG63 osteosarcoma cell line." (PMID 27716826, 2016). "Additionally, our preliminary study showed that METRNL is specially expressed in bone and overexpression of METRNL inhibited mineralized nodule formation by the MG63 osteosarcoma cell line." (PMID 27716826, 2016).
sarcopenia (1 paper, 2025). Progressive decline in muscle mass due to aging which results in decreased functional capacity of muscles. "In contrast, newer myokines/adipokines FNDC5, METRNL, RETN, and NAMPT, together with AdipoQ in sarcopenia, were uniformly negatively correlated, suggesting a counter-regulatory or compensatory circuit activated by mitochondrial stress." (PMID 40869253, 2025).
Simpson-Golabi-Behmel syndrome (1 paper, 2023). Simpson-Golabi-Behmel syndrome is a rare X-linked multiple congenital anomalies syndrome, characterized by pre- and postnatal overgrowth, distinctive craniofacial features, variable congenital malformations, organomegaly and an increased tumor risk. "Simpson-Golabi-Behmel Syndrome (SGBS) adipose cells were thermogenically activated using cAMP, and METRNL gene expression and METRNL protein released were analysed." (PMID 36936161, 2023).
cancer (3 papers, 2017 to 2024). A tumor composed of atypical neoplastic, often pleomorphic cells that invade other tissues. "In this study conducted in breast tissue with IDC, the increase in METRNL compared to healthy tissue supports the idea of METRNL being an important biomarker in the diagnosis of cancer." (PMID 39044875, 2024). "Although it is known that METRNL and asprosin are increased in some cancers, more studies are needed to elucidate their mechanism of action because they are new molecules." (PMID 39044875, 2024). "In addition, other clinical characteristics of the patients may need to be taken into account in order for METRNL and asprosin to be accepted as biomarkers in cancer diagnosis." (PMID 39044875, 2024).
tumor (2 papers, 2017 to 2025). "The authors showed that METRNL exposure induces bioenergetic failure of T cells and causes CD8+ T cells to become hypofunctional, and METRNL downregulation improves the anti-tumor function of these CD8+ T cells." (PMID 40507361, 2025). "Indeed, the GBM TME can affect the bioenergetic profile of anti-tumor CD8+ T cells through small molecules such as Meteorin-like (METRNL)." (PMID 40507361, 2025).
cardiovascular disease (1 paper, 2023). "METRNL expression was found to be negatively correlated with LFM, and interestingly, its expression was also found to be positively correlated with the known downstream cardiovascular disease (CVD) risk factors (VAT mass, VLDL, and circulating TG)." (PMID 38201289, 2023).
METRNL also shares sentences with these, for which no sentence is quoted: diabetes (3 papers); polycystic ovary syndrome (3); type 2 diabetes (3); metabolic disease (2); allergic respiratory disease (1); atherosclerosis (1); atopic dermatitis (1); Bardet-Biedl syndrome (1); bladder cancer (1); breast carcinoma (1); carotid atherosclerosis (1); cognitive deficits (1); colorectal adenocarcinoma (1); coronary artery disease (1); Glucose intolerance (1); heart failure (1); hypertriglyceridemia (1); infarction (1); infection (1); invasive ductal carcinoma (1); liver disease (1); liver fibrosis (1); malignant mesothelioma (1); multiple sclerosis (1); pancreatic cancer (1); prediabetes (1); prostate carcinoma (1); prurigo nodularis (1); psoriasis (1); pyometra (1).
A further 3 diseases each share a sentence with METRNL in 1 paper.